GPBAR1 (G protein-coupled bile acid receptor 1)
Description:
G protein-coupled receptor for bile acid. Bile acid-binding causes a conformation change that triggers signaling via guanine nucleotide-binding proteins (G proteins) and modulates the activity of downstream effectors, such as adenylate cyclase. GPBAR1 is coupled to G(s) G proteins and mediates activation of adenylate cyclase activity. Activated by bile acids, such as lithocholate, deoxycholate, chenodeoxycholate and cholate, in descending order. Apart from their role in lipid dietary absorption and cholesterol catabolism, bile acids act as an important signaling molecule, involved in processes, such as energy expenditure or tissue inflammation. GPBAR1-mediated signaling promotes energy expenditure and adiposity reduction in brown adipose tissue by activating adenylate cyclase, leading to DIO2 activation (By similarity). Involved in bile acid promoted GLP-1 secretion (By similarity).
Synonyms: M-BAR; BG37; TGR5; GPCR; GPCR19; GPR131; MGC40597
Tractability: Small molecule: a structure with a bound ligand is known; a high-quality ligand is known; it belongs to a druggable protein family. Antibody: UniProt places it where antibodies can reach, with high confidence; its Gene Ontology location is reachable by antibodies, with high confidence; UniProt predicts a signal peptide or a membrane-spanning region. PROTAC: a small molecule that binds it is known.
Target class: Family A G protein-coupled receptor; Steroid-like ligand receptor; Membrane receptor; Small molecule receptor (family A GPCR); Lipid-like ligand receptor (family A GPCR)
Chemical probes: CHEMBL3234871
Safety:
Unwanted effects reported when the protein is acted on. In parentheses: how it was acted on, where the effect was seen, and who reports it.
diffuse hyperplasia of the epithelium in the gallbladder (activation; gallbladder; source: Brennan et al. (2024))
fat necrosis (activation; adipose; source: Brennan et al. (2024))
hyperplasia of the periportal bile ducts (activation; liver; source: Brennan et al. (2024))
multifocal hepatocellular necrosis in liver (activation; liver; source: Brennan et al. (2024))
neutrophilic inflammation in the gallbladder (activation; gallbladder; source: Brennan et al. (2024))
Pancreatitis (activation; pancreas; source: Brennan et al. (2024))
periportal vasculitis/perivasculitis (activation; liver; source: Brennan et al. (2024))
Gene: Protein-coding gene on chromosome 2 (218,259,496 to 218,263,861, forward strand). Ensembl gene ENSG00000179921.
Subcellular location: Cell membrane
Pathways (Reactome):
Signal Transduction: Class A/1 (Rhodopsin-like receptors); G alpha (s) signalling events
Gene Ontology:
Molecular function: G protein-coupled bile acid receptor activity; protein binding; G protein-coupled receptor activity
Biological process: adenylate cyclase-activating G protein-coupled bile acid receptor signaling pathway; cellular response to bile acid; energy homeostasis; G protein-coupled receptor signaling pathway; positive regulation of cholangiocyte proliferation; positive regulation of ERK1 and ERK2 cascade
Cellular component: cytoplasm; plasma membrane; receptor complex; membrane
Genetic constraint (gnomAD): Loss-of-function variants: 17 observed, 16.15 expected, observed/expected ratio (o/e) 1.05, 90% interval 0.72 to 1.57. The upper end of that interval is the gene's LOEUF score, 1.57, which puts it in group 6 of 6, group 1 being the genes least tolerant of losing a copy. Missense variants: 398 observed, 430.1 expected, observed/expected ratio (o/e) 0.93, 90% interval 0.85 to 1. Synonymous variants: 193 observed, 204.8 expected, observed/expected ratio (o/e) 0.94, 90% interval 0.84 to 1.06.
Homologues: Orthologues: chimpanzee GPBAR1 (99% identical), macaque GPBAR1 (95% identical), rabbit GPBAR1 (90% identical), dog GPBAR1 (88% identical), pig GPBAR1 (87% identical), guinea pig GPBAR1 (83% identical), mouse Gpbar1 (83% identical), rat Gpbar1 (82% identical), Caenorhabditis elegans npr-28 (18% identical), Caenorhabditis elegans npr-26 (16% identical), Caenorhabditis elegans npr-25 (15% identical).
Diseases named in the same sentence as GPBAR1 in open-access papers:
GPBAR1 is named in the same sentence as 219 diseases in open-access papers, as found by Europe PMC text mining. Sharing a sentence is not in itself a finding about the gene and the disease. The quoted sentences say what the papers report.
Obesity (141 papers, 2010 to 2026). Accumulation of substantial excess body fat. "TGR5 (also known as Gpbar-1), a G- protein-coupled BA receptor, is a potential drug target useful to treat obesity and associated metabolic disorders." (PMID 36531484, 2022). "The G protein-coupled bile acid receptor 1 (GPBAR1), also known as TGR5, is implicated in diseases including atherosclerosis, type 2 diabetes, and obesity." (PMID 36355476, 2022). "TGR5 (G protein-coupled bile acid receptor 1) agonists improve mitochondrial β-oxidation of fatty acids and reduce renal lipid accumulation in obesity models." (PMID 40993041, 2025). "For example agonists of FXR and GPBAR1 can improve glucose and insulin sensitivity and increase energy metabolism which can prevent obesity and NAFLD." (PMID 37941122, 2023). "For all these reasons, the development of GPBAR1 agonists represents an intriguing strategy for the treatment of metabolic disorders like type II diabetes, obesity, inflammatory diseases and some types of cancer." (PMID 30792450, 2019). "The G-protein bile acid receptor 1 (GPBAR1) has emerged in the last decade as prominent target for the treatment of metabolic and inflammatory diseases including type 2 diabetes, obesity, and non-alcoholic steatohepatitis." (PMID 30792450, 2019). "This extract contains large amounts of oleanolic acid, which activates TGR5 (G protein-coupled bile acid receptor 1) and is reported to have an obesity-suppressing effect in humans." (PMID 31035323, 2019). "The G protein-coupled bile acid receptor (GPBAR1) has been recognized as a promising new target for the treatment of diverse diseases, including obesity, type 2 diabetes, fatty liver disease and atherosclerosis." (PMID 30013964, 2018). "The G protein-coupled bile acid receptor 1 (TGR5) is thought to be a promising drug target for metabolic diseases because its activation prevents obesity and hyperglycemia." (PMID 27845763, 2016). "In particular, GPBAR1/Gs interactions are involved in the prevention of diabetes and the reduction of inflammatory responses, making GPBAR1 a potential therapeutic target for several diseases, such as obesity or atherosclerosis." (PMID 40858717, 2025). "BA receptors, FXR and GPBAR1 may be involved in protecting kidney function in diabetes and obesity directly." (PMID 38429722, 2024). "Over the last decade, it has become clear that they are also potent signaling molecules, mainly via interaction with nuclear receptor FXR and membrane G protein-coupled receptor TGR5 (also known as GPBAR-1 or GPCR19), having substantial impact on health and disease including obesity and T2DM." (PMID 30761090, 2019). "Studies found that the selective intestinal FXR agonist fexaramine could improve obesity-related metabolic dysfunctions, and activate G protein-coupled bile acid receptor 1/Glucagon-like peptide-1 signaling to improve insulin sensitivity and increase adipose tissue browning." (PMID 34603061, 2021). "A notable proportion of network hubs—including FXR, GPBAR1, IL6, and TNF—were shared across multiple disease pathways, emphasizing the relevance of probiotic metabolites in modulating conditions such as type 2 diabetes, obesity, NAFLD, and IBD." (PMID 40612394, 2025). "Surprisingly, gavage with R. torques improved high-fat diet (HFD)-induced obesity, glucose homeostasis, and insulin sensitivity in mice by increasing DCA levels, resulting in G-protein-coupled bile acid receptor (GPBAR1/TGR5) activation and elevation of white adipose tissue thermogenesis." (PMID 40084870, 2025). "Interestingly, by increasing GPBAR–1 expression with the GPBAR–1 agonist INT–777, HFD–induced obesity is blunted." (PMID 37274345, 2023). "Both GPBAR1 and FFA1 are under investigation as candidate drug targets for increasing gut hormone secretion in humans, and thereby treating conditions such as type 2 diabetes and obesity." (PMID 29167062, 2018).
Obesity (continued). "Although definitive clinical studies are missing in this respect, the GPBAR-1 agonists might become an attractive therapeutic option for the treatment of nonalcoholic steatohepatitis (NASH), especially in patients with diabetes and obesity." (PMID 33266235, 2020). "GPBAR-1 KO mice on a high-fat diet exhibited significant fat accumulation with body weight gain compared with that of the wild-type mice, while in mice, the activation of GPBAR-1 by INT-777 stimulates the release of the incretin GLP-1, protecting from diabetes and obesity." (PMID 33266235, 2020). "Gpbar1−/− mice (TGR5) have a ~25% decrease in bile acid pool size but gain weight at the same rate or slightly more rapidly than wild‐type mice on both standard chow and high‐fat diets, indicating that this relatively small change in bile acid does not prevent diet‐induced obesity." (PMID 25626867, 2015). "However, our data suggest that there is a chance that GPBAR1/TGR5 agonists, that are currently developed as a novel therapeutic modality against obesity in humans, might not be effective." (PMID 20815878, 2010).
colitis (52 papers, 2011 to 2026). Inflammation of the colon. "Activation of GPBAR1 can alleviate colitis in mice by altering macrophage polarization from the pro-inflammatory M1 phenotype to the anti-inflammatory M2 phenotype." (PMID 40558546, 2025). "In contrast, GPBAR1-/- mice predominantly exhibit M1 macrophages, resulting in severe colitis when induced by TNBS." (PMID 40558546, 2025). "Lithocholic (LCA) and deoxycholic (DCA) acids were shown to reduce inflammation in a mouse model of colitis through the stimulation of the surface G protein-coupled bile acid receptor 1 (GPBAR1 or TGR5) in immune cells." (PMID 38514730, 2024). "A positive correlation occurred between GCG and GPBAR1 in human samples and animal models of colitis." (PMID 35406751, 2022). "Since these findings indicate that these three mouse models of inflammation cause a similar level of regulation of ACE2 in the colon, we then investigated how GPBAR1 regulates ACE2 mRNA expression in the mouse models of colitis." (PMID 35406751, 2022). "On the other hand, the administration of GPBAR1 agonist reverts intestinal inflammation in mouse models of colitis with a strong increase of IL-10 production." (PMID 34064187, 2021). "Thanks to this dual activity, the activation of GPBAR1 shift colonic macrophages from M1 pro-inflammatory phenotype to a M2 anti-inflammatory phenotype, relieving colitis in mouse models of the disease." (PMID 34064187, 2021). "Similar beneficial effects on chemically-induced colitis were evident with the GPBAR-1 agonists triterpenoids OA and betulinic acid, BIX02694." (PMID 33266235, 2020). "The GPBAR1 agonist BAR501 was shown to protect against oxazolone-induced colitis." (PMID 40426955, 2025). "For instance, patients with ulcerative colitis exhibit a reduction in endogenous levels of secondary BAs and that reconstitution of physiological levels of BAs by rectal administration of LCA mitigated murine colitis through a mechanism involving GPBAR1-dependent mitigation actions." (PMID 41228488, 2025). "FXR and GPBAR1 (also known as TGR5) are bile acid receptors expressed on monocytes and macrophages, and activation of these receptors have been shown to induce anti-inflammatory effects and protect against colitis in mice." (PMID 35529468, 2022). "Here, by using genetic and pharmacological approaches, we report that colonic expression of ACE2 is induced in response to intestinal inflammation in humans and rodent models of colitis in a GPBAR1-dependent manner and that the GPBAR1–GLP-1 axis mediates this regulation, overcoming inflammation." (PMID 35406751, 2022). "The results of these assays demonstrate that BAR501 significantly increases the expression of Gcg, the gene encoding for GLP-1 in mice, and that a direct correlation exists between Gpbar1 and Gcg expression in the colon of mice with colitis induced by oxazolone (p value = 0.0229)." (PMID 35406751, 2022). "In fact, GPBAR1 knock-out mice develop spontaneous inflammation in the colon with advancing age and furthermore, when stimulated with inflammatory agents, they develop colitis much more severe than wild-type mice." (PMID 34064187, 2021). "Importantly, a prior work utilizing Lgr5-Cre-driven GPBAR1 conditional knockout mice revealed that intestinal stem cells exhibited impaired self-renewal, reduced differentiation capacity, and delayed post-colitis regeneration, accompanied by disrupted YAP/SRC signaling pathway activation." (PMID 41228488, 2025). "Because the overwhelming role exerted by colon inflammation in regulating Ace2 mRNA expression in this region prevents gaining information on the role of GPBAR1 per se, we investigated whether activation of GPBAR1 in two rodent models of colitis directly modulates ACE2 mRNA expression." (PMID 35406751, 2022). "By comparing colonic mRNA levels of various BARs in colitis animals, most BARs levels were increased in PCDSS mice, such as Gpbar1(TGR5), Vdr, Nr1h3 (LXRα), Nr1h2 (LXRβ), Nr1i2 (PXR), and Nr1i3 (CAR)." (PMID 36050867, 2022).
colitis (continued). "Agonists of two bile acid receptors, TGR5 (GPBAR1) and FXR, have attracted the most attention as drug candidates, and their efficacy in preclinical models of colitis has been widely described." (PMID 36052074, 2022). "The association between GPBAR1 and NLRP3 has also been demonstrated, but most studies have mainly confirmed the effect of GPBAR1 on the NLRP3 inflammasome in the context of neuroinflammation, colitis, pancreatitis and nonalcoholic steatohepatitis (NASH)." (PMID 35095513, 2021). "TNBS and oxazolone induced colitis in mice, and the inflammation was attenuated by BAR501 a small molecule agonist for GPBAR-1." (PMID 33266235, 2020). "Because these data strongly highlight a direct correlation between GPBAR1 and GLP-1 expression and GLP-1 and ACE2, we then investigated whether blocking GLP-1 signaling in the TNBS model of colitis reverts upregulation of ACE2 in response to BAR501." (PMID 35406751, 2022). "Together, these data reaffirmed that Ace2 expression is upregulated in the colon following the induction of colitis and that the absence of Gpbar1 enhances this mechanism." (PMID 35406751, 2022).
diabetes (49 papers, 2011 to 2026). "GPBAR1/Gs protein interactions are implicated in the prevention of diabetes and the reduction of inflammatory responses, making GPBAR1 a potential therapeutic target for metabolic disorders." (PMID 40858717, 2025). "GPBAR-1 activation in the macrophages may be a promising approach to preventing insulin resistance and treating type 2 diabetes mellitus and associated inflammatory and metabolic disorders." (PMID 33266235, 2020). "TGR5, also called GPBAR1 or GPR131, is a bile acid–responsive G protein-coupled receptor, which plays a crucial role in protection against diet-induced diabetes through different cellular mechanisms." (PMID 31842453, 2019). "A member of the G protein-coupled receptor family, G protein-coupled bile acid receptor 1 (GPBAR1; also known as TGR5), has been recently identified as a drug target for diabetes treatment." (PMID 31871553, 2019).
atherosclerosis (44 papers, 2013 to 2025). A disease characterized by the build-up of fatty material and calcium deposition in the arterial wall resulting in partial or complete occlusion of the arterial lumen. "The G-protein coupled bile acid receptor 1 (GPBAR-1, also known as TGR5), known for its anti-inflammatory implications in the digestive tract, is an emerging target in mediating pro-inflammatory cytokines in atherosclerosis due to its high expression in both monocytes and macrophages." (PMID 29393918, 2018).
Insulin resistance (44 papers, 2015 to 2025). Increased resistance towards insulin, that is, diminished effectiveness of insulin in reducing blood glucose levels. "Activation of GPBAR1 has been associated with a reduction in insulin resistance and inflammatory response, with secondary BA more potent ligands than primary or tertiary BAs." (PMID 40347281, 2025). "Only a few studies exist on GPR119, free fatty acid receptor 1 (FFAR1/GPR40) and 4 (FFAR4/GPR120), and the bile acid receptor GPBAR1 (TGR5) as a developer of insulin resistance and β-cell dysfunction, receiving particular attention as targets for therapeutic interventions in diabetic patients." (PMID 35885041, 2022). "The discrepancy might be partly explained by the pollutant-generated activation of complex pathways (i.e., altered adipogenesis, liver, pancreatic and neurologic dysfunction, insulin resistance, and gut dysbiosis) which, in turn, promote GPBAR-1 activation as a protective mechanism." (PMID 33266235, 2020).
Hepatic steatosis (37 papers, 2013 to 2026). Steatosis is a term used to denote lipid accumulation within hepatocytes. "Furthermore, knockdown of the G protein-coupled bile acid receptor 1 gene in ingWAT reverses the beneficial effects of the loss of liver-innervating cholinergic neurons, leading to the reappearance of hepatic steatosis." (PMID 39436946, 2024).
type 2 diabetes (35 papers, 2011 to 2026). "The data discussed in this brief review indicate that GPBAR1 and FFARs 1, 2, 3 and 4 all represent potential pharmacological targets for improving impaired glucose homeostasis in type-2 diabetes and related metabolic disorders." (PMID 37484954, 2023). "We can suggest that 7-ELCA may be a prospective approach to the treatment of type II diabetes as the dual modulation of GPBAR1 and FXR has been supposed to be effective in the synergistic regulation of glucose homeostasis in the intestine." (PMID 34483922, 2021).